Y_RNA (Y RNA )
Gene: Miscellaneous RNA gene on chromosome 3 (127,202,372 to 127,202,473, reverse strand). Ensembl gene ENSG00000212556.
Homologues: Orthologues: chimpanzee Y_RNA (97% identical). Paralogues in human: Y_RNA (80% identical), RNY3P2 (79% identical), Y_RNA (79% identical), Y_RNA (78% identical), RNY3 (77% identical), Y_RNA (77% identical), Y_RNA (76% identical), RNY3P4 (75% identical), RNY3P9 (75% identical), Y_RNA (75% identical), RNY3P1 (75% identical), RNY3P14 (74% identical), and 89 more.